FNIP1 (folliculin interacting protein 1)
Description:
Binding partner of the GTPase-activating protein FLCN: involved in the cellular response to amino acid availability by regulating the non-canonical mTORC1 signaling cascade controlling the MiT/TFE factors TFEB and TFE3. Required to promote FLCN recruitment to lysosomes and interaction with Rag GTPases, leading to activation of the non-canonical mTORC1 signaling. In low-amino acid conditions, component of the lysosomal folliculin complex (LFC) on the membrane of lysosomes, which inhibits the GTPase-activating activity of FLCN, thereby inactivating mTORC1 and promoting nuclear translocation of TFEB and TFE3 (By similarity). Upon amino acid restimulation, disassembly of the LFC complex liberates the GTPase-activating activity of FLCN, leading to activation of mTORC1 and subsequent inactivation of TFEB and TFE3. Together with FLCN, regulates autophagy: following phosphorylation by ULK1, interacts with GABARAP and promotes autophagy. In addition to its role in mTORC1 signaling, also acts as a co-chaperone of HSP90AA1/Hsp90: following gradual phosphorylation by CK2, inhibits the ATPase activity of HSP90AA1/Hsp90, leading to activate both kinase and non-kinase client proteins of HSP90AA1/Hsp90. Acts as a scaffold to load client protein FLCN onto HSP90AA1/Hsp90. Competes with the activating co-chaperone AHSA1 for binding to HSP90AA1, thereby providing a reciprocal regulatory mechanism for chaperoning of client proteins. Also acts as a core component of the reductive stress response by inhibiting activation of mitochondria in normal conditions: in response to reductive stress, the conserved Cys degron is reduced, leading to recognition and polyubiquitylation by the CRL2(FEM1B) complex, followed by proteasomal (By similarity). Required for B-cell development.
Synonyms: KIAA1961; IMD93
Tractability: PROTAC: UniProt records ubiquitination sites on it; ubiquitination databases record sites on it; its protein half-life has been measured.
Gene: Protein-coding gene on chromosome 5 (131,641,714 to 131,797,017, reverse strand). Ensembl gene ENSG00000217128.
Subcellular location: Lysosome membrane; Cytoplasm, cytosol
Pathways (Reactome):
Cellular responses to stimuli: Amino acids regulate mTORC1
Gene Ontology:
Molecular function: ATPase inhibitor activity; enzyme activator activity; enzyme binding; protein binding; protein-folding chaperone binding
Biological process: B cell differentiation; negative regulation of lysosome organization; negative regulation of transcription by RNA polymerase II; positive regulation of protein-containing complex assembly; positive regulation of TOR signaling; positive regulation of TORC1 signaling; cellular response to starvation; immature B cell differentiation; negative regulation of TOR signaling; positive regulation of B cell apoptotic process; regulation of pro-B cell differentiation
Cellular component: cytoplasm; cytosol; FNIP-folliculin RagC/D GAP; lysosomal membrane
Genetic constraint (gnomAD): Loss-of-function variants: 32 observed, 109.15 expected, observed/expected ratio (o/e) 0.29, 90% interval 0.22 to 0.39. The upper end of that interval is the gene's LOEUF score, 0.39, which puts it in group 1 of 6, group 1 being the genes least tolerant of losing a copy. Missense variants: 1,076 observed, 1,345.9 expected, observed/expected ratio (o/e) 0.8, 90% interval 0.76 to 0.84. Synonymous variants: 441 observed, 454.58 expected, observed/expected ratio (o/e) 0.97, 90% interval 0.9 to 1.05.
Gene-disease validity (ClinGen):
ClinGen rates the evidence that FNIP1 causes each of these diseases.
FNIP1-associated syndrome (autosomal recessive): Definitive. Any immunodeficiency in which the cause of the disease is a mutation in the FNIP1 gene.
Homologues: Orthologues: chimpanzee FNIP1 (99% identical), dog FNIP1 (95% identical), rabbit FNIP1 (94% identical), guinea pig FNIP1 (93% identical), pig FNIP1 (93% identical), rat Fnip1 (91% identical), mouse Fnip1 (91% identical), tropical clawed frog fnip1 (73% identical), zebrafish fnip1 (61% identical), Drosophila melanogaster CG3764 (24% identical), Caenorhabditis elegans fnip-2 (17% identical). Paralogues in human: FNIP2 (48% identical).
Diseases named in the same sentence as FNIP1 in open-access papers:
FNIP1 is named in the same sentence as 58 diseases in open-access papers, as found by Europe PMC text mining. Sharing a sentence is not in itself a finding about the gene and the disease. The quoted sentences say what the papers report.
Renal cyst (8 papers, 2018 to 2025). A fluid filled sac in the kidney. "In this study, we found that loss of Fnip1 was sufficient to increase mTORC1 activation primarily in renal epithelial cells lining renal cysts." (PMID 29897930, 2018). "In this study, we utilized mice with constitutive deletion of the Fnip1 gene to show that the loss of Fnip1 is sufficient to result in renal cyst formation, which was characterized by decreased AMPK activation, increased mTOR activation, and metabolic hyperactivation." (PMID 29897930, 2018). "Disruption of FNIP1 resulted in the enlarged kidney size and significantly increased renal cyst formation." (PMID 36693108, 2023). "Nuclear Tfeb in renal cysts and precystic lesions was observed compared with heterozygous Fnip1/2fl/+:Ksp-Cre control samples." (PMID 36794754, 2023). "Additional features reported in patients with FNIP1 LOF include myopathy, renal cysts, and central nervous involvement (developmental delay, microcephaly, and others)." (PMID 39537849, 2024). "Although Fnip1-null mice do not develop renal tumors, small renal cysts develop consistently and are characterized by increased mTORC1 activation and alterations in the expression of genes associated with PKD in humans, including amino acid and ion transporters, cell adhesion, and inflammation." (PMID 40699689, 2025). "However, whole body deletion of Fnip1 also leads to multiple nonmuscle system derangements including immune cell development defect, cardiomyopathy, and renal cyst formation." (PMID 33780446, 2021).
cardiomyopathy (5 papers, 2021 to 2025). A disease of the heart muscle or myocardium proper. "FNIP1-deficient mice exhibit profound B-cell maturation defects, metabolic abnormalities, and cardiomyopathy, mirroring many of the clinical manifestations observed in human FNIP1 deficiency." (PMID 40699689, 2025). "In this study, we describe a patient found to harbor a novel homozygous variant in FNIP1, located in exon 1, resulting in B-cell lymphopenia, agammaglobulinemia, recurrent infections, and cardiomyopathy." (PMID 39537849, 2024). "Genetic variants in Folliculin interacting protein 1 (FNIP1) were recently discovered as monogenic causes for immunodeficiency and cardiomyopathy, with only a few patients diagnosed thus far." (PMID 39537849, 2024). "The index patient in our study (subject II-4) exhibited several clinical and laboratory features consistent with previously reported cases of FNIP1 LOF variants, including agammaglobulinemia, recurrent infections, chronic diarrhea, and cardiomyopathy." (PMID 39537849, 2024). "In addition to B-cell deficiency, FNIP1 loss leads to cardiomyopathy, which phenocopies AMPK gain-of-function mutations, consistent with a failure of FNIP1 to regulate AMPK-mediated signaling." (PMID 35883484, 2022).
agammaglobulinemia (4 papers, 2023 to 2025). A decreased level of serum immunoglobulins. "FNIP1 deficiency is characterized by profound B-cell lymphopenia and antibody deficiency, often resulting in hypogammaglobulinemia or agammaglobulinemia." (PMID 40699689, 2025). "FNIP1 deficiency is currently classified as a predominantly antibody deficiency, with patients exhibiting severe B-cell deficiency and hypogammaglobulinemia or agammaglobulinemia." (PMID 40699689, 2025). "FNIP1 LOF in humans is associated with immunodeficiency characterized by hypogammaglobulinemia, neutropenia, and recurrent infections along with cardiac involvement, including hypertrophic cardiomyopathy (HCM), tachyarrhythmias, and pre-excitation syndromes." (PMID 39537849, 2024). "FNIP1 loss-of-function should be considered in patients presenting in infancy with cardiac manifestations along with agammaglobulinemia (and B-cell lymphopenia)." (PMID 39537849, 2024). "FNIP1 loss-of-function (LOF) is a monogenic disease-causing disorder that results in hypogammaglobulinemia with syndromic features." (PMID 39537849, 2024). "Further underscoring the pathological importance of the FNIP1, mutations in FNIP1 are recognized to cause severe B-cell development defect, agammaglobulinemia, hypertrophic cardiomyopathy and pre-excitation syndrome in humans." (PMID 37932296, 2023). "FNIP1 LOF should be considered in patients presenting during infancy with cardiac manifestations along with agammaglobulinemia (and B-cell lymphopenia)." (PMID 39537849, 2024). "In 2012, two research groups independently identified that disruptions in gene-encoding murine Fnip1 resulted in the absence of peripheral B-cells and agammaglobulinemia." (PMID 40699689, 2025).
Obesity (4 papers, 2022 to 2025). Accumulation of substantial excess body fat. "In contrast, we did not detect any relationship between the expression of FNIP1 or miR-181b and phenotypic characteristics related to overweight or obesity." (PMID 36316722, 2022).
hypertrophic cardiomyopathy (3 papers, 2023 to 2025). A condition in which the myocardium is hypertrophied without an obvious cause. "Hypertrophic cardiomyopathy in FNIP1-deficient mice is associated with increased left ventricular (LV) mass." (PMID 40699689, 2025).
Immunodeficiency (3 papers, 2021 to 2025). Failure of the immune system to protect the body adequately from infection, due to the absence or insufficiency of some component process or substance. "Given the profound B-cell lymphopenia and neutropenia, it remains challenging to delineate the precise contribution of these immunodeficiency defects from potential dysfunctions in other cell types affected by FNIP1 deficiency." (PMID 40699689, 2025). "In this study, we aim to describe a novel genetic variant in FNIP1, causing immunodeficiency with cardiac involvement." (PMID 39537849, 2024). "To date, seven patients with FNIP1-associated immunodeficiency have been reported in the literature, most of whom presented typical clinical features during infancy." (PMID 39537849, 2024). "In this study, we describe a patient harboring a novel genetic variant in FNIP1 causing immunodeficiency with cardiac involvement." (PMID 39537849, 2024). "Loss of folliculin interacting protein 1 (encoded by FNIP1) due to inactivating mutations results in immunodeficiency and heart defects due to disruption of essential metabolic regulators AMPK and mTOR." (PMID 34957217, 2021). "Additionally, given the profound immune defects associated with FNIP1 deficiency, hematopoietic stem cell transplantation (HSCT) could be considered in severe cases, particularly in those with life-threatening infections or progressive immunodeficiency." (PMID 40699689, 2025).
muscular dystrophy (3 papers, 2016 to 2023). Muscular dystrophy (MD) refers to a group of more than 30 genetic diseases characterized by progressive weakness and degeneration of the skeletal muscles that control movement. "FNIP1 plays an important role in regulating the specificity of skeletal muscle fiber type, anti-fatigue and susceptibility to muscular dystrophy." (PMID 37341987, 2023). "Functionally, inhibition of Fnip1 by miR‐499a‐5p results in improved mitochondrial function in myocytes and improved mitochondrial capacity in mice with muscular dystrophy." (PMID 34984856, 2022). "Based on our data, it is likely that the inhibition of Fnip1 leading to activation of PGC‐1α signaling could contribute to the prevention of muscular dystrophy in 499Tg/mdx mice." (PMID 27506764, 2016). "Moreover, Fnip1 knockout mice in an mdx genetic background have recently been shown to be protected against muscular dystrophy." (PMID 27506764, 2016).
polycystic kidneys (3 papers, 2017 to 2023). "Recent studies indicated that FNIP1/FNIP2 double knockout mice display enlarged polycystic kidneys and renal carcinoma, which phenocopies FLCN knockout mice, suggesting that these two proteins function together to suppress renal cancer." (PMID 28039480, 2017). "Whole-body FNIP1+/−FNIP2−/− mice develop renal cancer while kidney-specific FNIP1−/−FNIP2−/− mice displayed enlarged polycystic kidneys." (PMID 28039480, 2017). "Whereas kidney-specific deletion of the Bhd gene in mice is known to result in polycystic kidney disease (PKD) and renal cell carcinoma, the roles of Fnip1 in renal cell development and function are unclear." (PMID 29897930, 2018).
renal carcinoma (3 papers, 2017 to 2025). A carcinoma arising from the epithelium of the renal parenchyma or the renal pelvis. "Because inactivating mutations in the BHD gene encoding Folliculin result in renal cancer, we sought to determine if loss of Fnip1 alters kidney development and/or function in Fnip1-null mice, which were previously generated using ENU chemical mutagenesis." (PMID 29897930, 2018). "In renal cancer, reduced expression of FNIP1 is correlated with increased tumor aggressiveness and malignancy." (PMID 40143966, 2025). "Heterozygous FNIP1/homozygous FNIP2 double knockout mice developed renal cancer at 24 months, akin to heterozygous FLCN knockout mouse models, thereby reinforcing the significance of FNIP1 and Fnip2 in tumor suppression and suggesting potential molecular targets for novel renal cancer therapies." (PMID 40143966, 2025). "Although disruption of Folliculin is known to predispose to renal cancer in humans, and PKD and renal cancer in mice, a specific role for Fnip1 has not been previously demonstrated." (PMID 29897930, 2018). "To investigate the role of β-TRCP-mediated FNIP degradation in renal cancer cell growth, we manipulated UOK-257-2 cells by depleting FNIP1/FNIP2 and reintroducing FNIP2-WT or non-degradable FNIP2-3A." (PMID 28039480, 2017).
breast carcinoma (2 papers, 2021 to 2022). "The calcineurin regulatory subunit PPP3R1 shows elevated expression in ER− breast cancer, whereas positive regulators of Rag C/D, including folliculin complex members FLCN and FNIP1, along with MAP4K3, are decreased in ER− breast cancer patients." (PMID 36372230, 2022). "Moreover, TET3 knocked-down cells under normoxia exhibited an identical alternative splicing pattern of ESRP1 targets (hMENA, SLK, SCRIB, RALGPS2, SLC37A2, FNIP1, CD44, and ARHGEF1) as the hypoxic breast cancer cells." (PMID 34362878, 2021).
cyst (2 papers, 2018 to 2023). A sac-like closed membranous structure that may be empty or contain fluid or amorphous material. "To determine why loss of Fnip1 could result in increased renal weight and cyst formation, we measured activation of AMPK and the mTOR pathways by immunoblotting and immunohistochemistry (IHC)." (PMID 29897930, 2018).
renal tumor (2 papers, 2010). "This study will shed light on the understanding of FLCN/FNIP1/FNIP2/AMPK function and the downstream target genes and signaling pathways that are important in tumorigenesis, providing insight into therapeutic targets for treatment of renal tumors that develop in BHD syndrome and translocation RCC." (PMID 21209915, 2010).
Alzheimer disease (1 paper, 2023). A progressive, neurodegenerative disease characterized by loss of function and death of nerve cells in several areas of the brain leading to loss of cognitive function such as memory and language. "MEG3 (ENST00000398461)/hsa-let-7d-5p/ATF6B axis showed importance in Parkinson’s and late Alzheimer’s diseases, while AC092687.3/hsa-let-7e-5p/[SREBF2, FNIP1, PMAIP1] and SDCBP2-AS1 (ENST00000446423)/hsa-miR-101-3p/MAPK6 axes are probably related to Alzheimer’s disease development and pathology." (PMID 38027526, 2023).
Bovine mastitis (1 paper, 2025). INFLAMMATION of the UDDER in cows. "This study showed that FNIP1 has the potential as a novel target for the prevention and control of bovine mastitis." (PMID 41206543, 2025). "These conclusions have provided the underlying molecular mechanism of K. pneumoniae-induced bovine mammary gland damage, suggesting that FNIP1 is a promising target for control of K. pneumoniae-induced bovine mastitis." (PMID 41206543, 2025).
cognitive delay (1 paper, 2025). "Developmental or cognitive delay was reported in 6 of 10 cases, suggesting that FNIP1 plays a role in neurodevelopment." (PMID 40699689, 2025). "Additionally, some patients exhibit neurological and muscular manifestations, including developmental delay, hypotonia, and structural brain abnormalities, further supporting the hypothesis that FNIP1 plays a role in multiple organ systems." (PMID 40699689, 2025).
dementia (1 paper, 2023). Loss of intellectual abilities interfering with an individual's social and occupational functions. "Moreover, most FLCN mutations isolated from BHD patients are loss of function leading to decreased protein stability or inability to interact with FNIP1/2, likewise the C9orf72 repeat expansion found in ALS and dementia cases results in a loss of function due to reduced C9orf72 protein expression." (PMID 38249578, 2023).
heart failure (1 paper, 2023). Inability of the heart to pump blood at an adequate rate to meet tissue metabolic requirements. "This FNIP1-macrophage regulatory circuit shows promise for the identification of therapeutic targets aimed at enhancing blood flow recovery in a variety of ischemic disease states such as peripheral artery disease and heart failure." (PMID 37932296, 2023).
Hepatic steatosis (1 paper, 2025). Steatosis is a term used to denote lipid accumulation within hepatocytes. "Second, mice deficient in FNIP1 are resistant to diet-induced hepatic steatosis; consistent with this, aggregated ultra-rare variants in FNIP1 were negatively associated with predicted PDFF." (PMID 40065360, 2025).
ischemia (1 paper, 2023). A hypoperfusion of the BLOOD through an organ or tissue caused by a PATHOLOGIC CONSTRICTION or obstruction of its BLOOD VESSELS, or an absence of BLOOD CIRCULATION. "However, it has yet to be unraveled whether FNIP1 signaling is implicated in controlling functional angiogenesis in skeletal muscle, and especially in the setting of ischemia." (PMID 37932296, 2023). "The robust induction of muscle revascularization by myofiber FNIP1 deficiency, and its critical function in response to limb ischemia, strongly implicates myofiber FNIP1 as a powerful regulator of the angiogenic response to ischemia." (PMID 37932296, 2023). "In this study, we uncovered a crucial role for myofiber FNIP1 in the control of skeletal muscle functional angiogenesis and the governance of muscle revascularization from ischemia." (PMID 37932296, 2023). "Here we show that FNIP1 plays a critical role in controlling skeletal muscle functional angiogenesis, a process pivotal for muscle revascularization during ischemia." (PMID 37932296, 2023). "To determine the role of FNIP1 in ischemic revascularization, we applied unilateral hindlimb ischemia to both FNIP1 MKO and Fnip1f/f littermate mice, and we assessed macrophage recruitment and neoangiogenesis after the induction of hindlimb ischemia in both the contralateral and ischemic muscles." (PMID 37932296, 2023).
kidney cancer (1 paper, 2021). Primary or metastatic malignant neoplasm involving the kidney. "When FNIP1 and FNIP2 are inactivated simultaneously, mice develop kidney cancer." (PMID 33459596, 2021).